MIR6818 (microRNA 6818)
Synonyms: hsa-mir-6818
Gene: MicroRNA gene on chromosome 22 (30,007,049 to 30,007,113, forward strand). Ensembl gene ENSG00000275818.
Homologues: Orthologues: chimpanzee MIR6818 (100% identical).